IL1B (interleukin 1 beta)
Diseases named in the same sentence as IL1B in open-access papers (continued):
Sharing a sentence is not in itself a finding about the gene and the disease.
cervical carcinoma (continued). "Previous studies have suggested that altering IL‐1β expression may influence the proliferation and migration of cervical cancer cells." (PMID 41025546, 2025). "In cervical cancer HeLa cells cultured with fluoride concentrations of 1–50 mg/L for 48 h, there was a strong increase in IL-1β, IL-6, and TNFα levels in the supernatant at the lowest concentration (1 mg/L), followed by a significant decrease at higher concentrations." (PMID 40497976, 2025). "CD200Fc inhibits NLRP3 activation in cervical cancer cells by reducing IL-1β production." (PMID 39769450, 2024). "In addition, a shorter OS time for postoperative patients with cervical cancer was observed between IL-1β high and IL-1β low (40.6 months vs. 82.0 months; P = 0.038) and between IL-8high and IL-8low (41.2 months vs. 82.0 months; P = 0.062)." (PMID 36053326, 2023). "In our study, the result revealed that rs3136558 and rs1143630 of IL‐1B may be protective loci for development of cervical cancer." (PMID 31222982, 2019). "IL‐1B mRNA expression was significantly increased in cervical cancer tissues compared with that in normal tissues (p < 0.01), suggesting an important role of IL‐1B in the development of cervical cancer." (PMID 31222982, 2019). "To date, less study has been conducted for investigating the association between IL‐1B polymorphisms and the susceptibility to cervical cancer, and there has been no relevant reported data in Chinese Uygur populations." (PMID 31222982, 2019). "Furthermore, knock down of the viral oncoproteins using siRNA for 16E6E7 restored the ability of a cervical cancer-derived cell line (SiHa HPV16+) to produce IL-1β in response to Nigericin, poly dA:dT and 16QsV." (PMID 30089163, 2018). "It appears that IL-1β can contribute to the pathogenesis of HPV-infected cervical carcinoma." (PMID 28402258, 2017). "Here, a strong reduction of IL-1β in immE6 and immE6/E7 cells and its complete absence in cervical carcinoma cell lines could be discerned." (PMID 23935506, 2013). "Hence, when tumor progression occurs, cervical cancers apparently use an additional strategy to inhibit the inflammatory response by diminishing IL-1β expression at the transcriptional level via gene silencing." (PMID 23935506, 2013). "The clinical relevance of our results was further confirmed in HPV-positive tissue samples, where a gradual decrease of IL-1β towards cervical cancer could be discerned." (PMID 23935506, 2013). "Conversely, we raised the question whether the stability of ectopically expressed pro-IL-1β is also affected when introduced into SiHa cervical carcinoma cells, which lack endogenous transcription of the corresponding gene." (PMID 23935506, 2013). "One of the primary mechanisms of cytokine storm in cervical cancer is the excessive release of cytokines such as IL-6, TNF-α, IL-1β, and IL-8." (PMID 41497141, 2026). "It identifies CST7, along with IL1B and ITGA5, as three crucial genes that play a vital role in the evolution of cervical cancer." (PMID 39552709, 2024). "By up-regulating CST7 and down-regulating IL1B and ITGA5, cervical cancer cells’ proliferation ability and invasion ability were successfully reduced." (PMID 36969161, 2023). "We then performed cellular experiments to investigate the role of CST7, IL1B and ITGA5 in cervical cancer cells." (PMID 36969161, 2023). "To explore the potential role of IL1b, CST7, and ITGA5 in the immune microenvironment, we downloaded single-cell data of cervical cancer in GEO to validate our results and explore a more precise transcriptional landscape." (PMID 36969161, 2023). "Thus, LPIN2 may affect the prognosis of patients with cervical cancer via IL-1β." (PMID 34789197, 2021). "In previous studies, T. vaginalis infection induced the production of inflammatory cytokines such as IL-1β, IL-6, CCL2 and CXCL8 in prostate epithelial cells as well as cervical cancer cells." (PMID 32196489, 2020).
cervical carcinoma (continued). "In a study using LPS-stimulated human CC cells, human SiHa and Caski cells (HPV-16-infected cervical cancer cell lines), the mRNA and protein levels of inflammasome components, such as NLRP3, pro-IL-1β, IL-1β, and caspase-1, was significantly increased." (PMID 33584639, 2020). "Using an inflammation model, human cervical cancer cells, positive for HPV-16 and treated with lipopolysaccharide (LPS), have indeed displayed increased levels of NLRP3, IL-1β, processed IL-1β, and cleaved caspase-1." (PMID 30837326, 2019). "Enhanced the antioxidant enzyme activities, and reduced levels of IL-1b, IL-6, and TNF-α in rats with cervical cancer." (PMID 30410443, 2018). "We next wanted to determine if IL-1β and IRF6 transcripts were down regulated in cervical cancer patients." (PMID 30089163, 2018). "In our experiment, different SMEDDS compositions were also investigated in the presence of IL-1-β and TNF-α on human cervical cancer HeLa cells." (PMID 26197311, 2015). "Thus, our data corroborates other results from our research group, in which a decrease in cytokine levels (IL-8, IL-1β) and ERK and p38 was also observed in HeLa, SiHa and CaSki cervical cancer cells after treatment with piperine." (PMID 38891950, 2024). "According to Transwell data, the capacity of cervical cancer cells to migrate was dramatically reduced when IL1B and ITGA5 were knocked down and CST7 was overexpressed in comparison to the control group, similarly, the invasive ability of cervical cancer cells was significantly down-regulated." (PMID 36969161, 2023). "Since cervical carcinoma patients often have persistent HPV infection, Nr‐CWS may promote the function of IL‐6 and IL‐1β against foreign pathogens." (PMID 34994088, 2022). "Similarly, in human cervical carcinoma cells (Hela), HIF-1α, IL-1β, IL-6, and IFN-β mRNAs were promoted by VSV infection, HSV-1 infection and poly(I: C) treatment and HIF-1α protein was induced by VSV infection, HSV-1 infection or poly(I: C) treatment." (PMID 34408131, 2021). "In order to further verify our screening results, we selected C6- quercetin, an important active compound in the treatment of cervical cancer by Hedyotis diffusa, for molecular docking with the core targets IL1B and IL6 which have prognostic value for cervical cancer respectively." (PMID 34975504, 2021). "Although RIPK3 contributes to the generation of active IL-1β in other cell types, the release of IL-1β from PolyIC-stimulated cervical cancer cells was negligible and did not contribute significantly to DC stimulation." (PMID 25888634, 2015). "To get insights on how this central cytokine is regulated, we monitored the processes that modulate the NALP3 inflammasome complex and in turn IL-1β secretion using primary and HPV16-immortalized human keratinocytes as well as HPV-positive cervical carcinoma cells as experimental model system." (PMID 23935506, 2013). "ImmE6 and immE6/E7 cells only released small amounts of IL-1β, while cervical carcinoma cell lines completely failed to secrete IL-1β." (PMID 23935506, 2013). "Moreover, abrogation of IL-1β availability during HPV-induced carcinogenesis seems to be a two-step mechanism, since cervical carcinoma cells as well as human cervical tumor tissues showed either a strongly reduced or even an absence of the corresponding mRNA." (PMID 23935506, 2013). "Moreover, a complete lack of IL-1β gene expression has also been observed in HPV-positive cervical carcinoma cell lines." (PMID 35047989, 2021). "Also neither IRF6 nor IL-1β mRNA levels were suppressed when analysing the data set from the TCGA cervical carcinoma cohort." (PMID 30089163, 2018).
cervical carcinoma (continued). "HeLa cervix carcinoma cells do not express 5-LO and readily upregulate PGE2 formation upon treatment with TNFα and IL-1β (T/IL) within hours." (PMID 35126121, 2021).
mucositis (60 papers, 2010 to 2026). Mucositis is inflammation and damage of the mucous membranes lining the mouth and other parts of the gastrointestinal (GI) tract. "The cytokines Il-1β and Tnf have previously been implicated in the initiation and maintenance of mucositis via NF-kB." (PMID 36591502, 2022). "IL-1β is also responsible for exacerbating mucositis by causing the disruption of tight junctions in the intestines of mice." (PMID 32707913, 2020). "In mucositis mice, 5-FU caused an increase in IL-1β concentration." (PMID 31921383, 2019). "Mucositis results in a high inflammatory response via the up-regulation and activation of various transcription factors, ultimately causing elevations in circulating proinflammatory cytokines, in particular IL-1β and TNF-α." (PMID 29872383, 2018). "Nevertheless, reduced TNFα and IL-1β expression could alleviate mucositis-associated pain sensation." (PMID 28258409, 2017). "Chemotherapy-induced mucositis is exacerbated by increased levels of inflammatory cytokines such as IL-1β and TNF-α, which are important mediators of inflammation." (PMID 40524059, 2025). "Due to the few available studies, meta‐analyses comparing patients with mucositis to healthy controls and patients with peri‐implantitis to those with mucositis were conducted only for IL‐1β and IL‐6." (PMID 40101934, 2025). "Regarding IBDs, GDF11 was able to ameliorate UC in a mice model through inhibition of NLRP3 inflammasome complex, the main responsible for the maturation of pro-inflammatory cytokine IL-1β and markedly present in mucositis induced by 5-FU." (PMID 37138633, 2023). "Both IL-6 and IL-1β were observed to be significantly higher in peri-implant mucositis compared to healthy controls." (PMID 37384298, 2023). "The present regression analysis results reflect that an increased PD is correlated with higher PISF IL-1β levels or vice versa in patients with peri-implant mucositis." (PMID 34585876, 2021). "Numerous studies have revealed elevated productions of the inflammasome-dependent cytokines IL-1β and IL-18 during clinical and experimental chemotherapy-induced mucositis." (PMID 34310611, 2021). "NF-κB positively regulates the expression of TNF-α and IL-1β, proinflammatory cytokines involved in the amplification of mucositis signals." (PMID 33406583, 2021). "It was demonstrated that IL-1β is responsible for the increased permeability of the mucosal barrier that occurs in an early phase of mucositis, due to dysregulation of epithelial tight junctions." (PMID 33225965, 2020). "Further evidences are mandatory to confirm the correlation between high-grade mucositis development and IL-6 or IL-1β levels in RT treated patients." (PMID 33028357, 2020). "Studies in mice suggest that epithelial tight junction dysfunction and mucositis significantly improve with antibody neutralization of IL-1β." (PMID 31888063, 2019). "Consumption of P. freudenreichii WT however reduced this 5-FU-induction of IL-1β in the context of mucositis (p<0.01)." (PMID 31921383, 2019). "Moreover, the NF-κB pathway activates the NLRP3 inflammasome complex which is the main responsible for the maturation of pro-inflammatory cytokine IL-1β and is markedly present in mucositis induced by 5-FU." (PMID 37138633, 2023). "In contrast, Dio efficaciously suppressed the expression of NF-κB downstream pro-inflammatory cytokines, including TNF-α, IL-6 and IL-1β in the ileums of CDDP-induced mucositis rats, and substantially promoted the production of the immunoregulatory mediators IL-10." (PMID 35457248, 2022). "However, TNF-α and IL-1β levels in the sera and all tissues reduced significantly in the Mucositis + ALA group compared to the Mucositis group (p < 0.05–0.0001)." (PMID 36290656, 2022). "Therefore, it is believed that TNF-α, IL-1β and IL-6 are involved in mucositis and have been the targets of inhibition." (PMID 34310611, 2021).
mucositis (continued). "In fact, expressions of TNF-α, IL-1β and IL-6 were also found to be increased in response to the 5-FU treatment, indicating that inflammatory cytokines play a key role in the pathogenesis of mucositis induced by chemotherapy and radiotherapy." (PMID 34310611, 2021). "TNF-α, IL-6, IL-1β, and cell apoptosis played a critical role in the development of mucositis." (PMID 33841399, 2021). "Mucosal barrier breach induced by IL-1β has been proposed as a trigger of mucositis onset." (PMID 31888063, 2019). "Importantly, IL-1β is one of the inflammatory mediators that is reportedly released during mucositis." (PMID 28403142, 2017). "The protective role of MyD88 and TLR2 and TLR9 in irinotecan-induced mucositis was associated with a pronounced reduction of the local inflammatory reaction, as detected by the measurement of myeloperoxidase activity and COX–2 and IL–1β production." (PMID 26440613, 2015). "Regarding mediators that might be altered by ApoE mimetic peptides, TNF-α and IL-1β are important pro-inflammatory cytokines activated by NF-κB pathway, which is up-regulated during the pathogenesis of 5-FU-induced mucositis." (PMID 22524518, 2012). "Its role in potentiating inflammatory and immune responses by inducing various proinflammatory cytokines production such as TNF, IL-6 and IL-1β involved in the development of mucositis has been widely recognised with the use of animal models and in the clinical setting." (PMID 22973511, 2012). "This study has shown for the first time, using the fractionated radiotherapy-induced mucositis rat model, that mRNA levels of pro-inflammatory cytokines, IL-1β, IL-6 and TNF, are significantly upregulated in the intestines following long term radiotherapy when compared to short term radiotherapy." (PMID 20233440, 2010). "Meta‐analyses confirmed the link of IL‐1β increased concentrations with peri‐implant diseases, reporting statistically significant mean differences between 124 patients with peri‐implantitis and 75 with mucositis compared with 192 and 147 healthy subjects, respectively." (PMID 40101934, 2025). "IL-1β, TNF-α, and IL-6 were elevated during the third week of therapy, related to the development of worse mucositis in the oral cavity." (PMID 41220465, 2025). "For example, promoter SNPs in interleukin-1 beta (IL1B) and tumor necrosis factor alpha (TNF) were related to mucositis after 5-FU treatment in a Japanese population." (PMID 37162533, 2023). "This study showed that proinflammatory cytokines IL-1β and TNF-α are elevated in Mucositis group’s sera and tissues (the stomach, small intestine, or large intestine)." (PMID 36290656, 2022). "The TNF-α and IL-1β levels in sera and all tissues of animals in the Mucositis group were significantly higher when compared to Control, ALA and Mucositis + ALA groups (p < 0.05–0.0001)." (PMID 36290656, 2022). "It was observed that the increase in IL-1β and TNF-α levels in Mucositis rats can be reversed by ALA treatment." (PMID 36290656, 2022). "In patients with peri-implant mucositis, PISF suPAR (p < 0.001) and galectin-1 (p < 0.001) levels correlated with PISF IL-1β levels." (PMID 34585876, 2021). "Correspondingly, in the present study, we observed increased levels of COX-2, iNOS, IL-8, IL-1β, and TNF-α in mice with CPT11-induced mucositis." (PMID 34795594, 2021). "NF-κB activation triggers the activation of multiple signaling pathways for the synthesis of different pro-inflammatory cytokines involved in various stages of mucositis, including TNF, IL-1β, and IL-6." (PMID 31936237, 2020). "Pro-inflammatory cytokines regulated by NF-κB, such as IL-6, IL-1β and TNF-α, account for an important mechanistic component in the pathogenesis of mucositis." (PMID 28968968, 2017). "Chang CT noted that the levels of proinflammatory cytokines, such as IL-1β and TNF-α, were elevated in the oral tissue with mucositis developed due to chemotherapy." (PMID 27812611, 2016).
mucositis (continued). "In the past decade, active research has been conducted to define the pathogenesis of mucositis and the role of proinflammatory cytokines TNF-α, IL-6, and IL-1β." (PMID 22973511, 2012). "NFκB is considered a key “driver” of chemotherapy-induced mucositis as its activation correlates with the production of TNF, IL-6 and IL-1β the hallmarks of mucositis inflammation." (PMID 22973511, 2012). "This transcription factor, which can also be directly activated by RT and/or CT, induces gene expression of proinflammatory cytokines such as interleukin-6 (IL-6), interleukin-1β (IL-1β), and tumor necrosis factor α (TNF-α), which are apparently increased in mucositis." (PMID 38473311, 2024). "Similarly, radiation‐induced oral mucositis is associated with a significant increase in inflammatory cytokines such as IL1β and TNF‐α and alleviation of mucositis led to a significant decrease in inflammatory cytokines levels." (PMID 35810384, 2022). "During RT regimen, high-grade mucositis is more probably detectable either in patients characterized by a HPV/p16-negative status or in those producing an elevated salivary cytokine, IL-6 and IL-1β, concentration." (PMID 33028357, 2020). "Despite the expression levels of some proteins involved in the inflammation response, such as TNF-α or IL-1β, partially correlate with mucositis process, their presence does not exclude others mucositis-independent inflammation events." (PMID 33028357, 2020). "The aim of this study was to evaluate the levels of salivary biomarkers IL-1β, IL-10, RANK, OPG, MMP-2, TG-β and TNF-α in individuals with diagnosis of peri-implant mucositis in the absence or presence of periodontal and peri-implant maintenance therapy (TMPP) over 5 years." (PMID 30810638, 2019). "Interestingly, whilst IL-1β and TNF-α are key proinflammatory cytokines instigating sickness behavior responses, they also play a pivotal role in the pathogenesis of mucositis." (PMID 29872383, 2018). "They found an elevation in serum levels of cytokines IL-6, TNF-α and IL-1β which correlated with mucositis severity, and also showed that Amifostine did not reduce mucositis severity." (PMID 20184737, 2010). "Mucositis reportedly consists of steps beginning with the formation of reactive oxygen species (ROS), progressing with the release of proinflammatory cytokines, such as tumor necrosis factor (TNF-α) and interleukin-1 beta (IL-1 β), resulting in mucosal damage, infection, and cell death." (PMID 27812611, 2016).